CXCL1 (C-X-C motif chemokine ligand 1)
Diseases named in the same sentence as CXCL1 in open-access papers (continued):
Sharing a sentence is not in itself a finding about the gene and the disease.
lung cancer (continued). "Both cytokines (IL-6, 10, 17, 27, 35; TNF-α; IFN-γ; TGF-β) and chemokines (CCL-2, 5, 18; CCR-4; CXCR-4; CX3CL-1; CXCL-1, 5, 8, 13) are very commonly targeted for lung cancer treatment, considering their biomarker roles." (PMID 34336101, 2021). "Silencing of CXCL1 in a 3LL mouse lung cancer model inhibits tumor growth and TAN mediated immunosuppression." (PMID 34168563, 2021). "One other finding was that CXCL-1 protein was found in higher amounts in ADC patients compared to other types of lung cancer." (PMID 34336101, 2021). "We employed mouse Lewis lung carcinoma cell line and human lung cancer cell line H460, which expressed CXCR2 on the surface and secreted CXCR2-associated chemokines, such as CXCL1, CXCL2, CXCL5 and MIF." (PMID 33814009, 2021). "Kaplan-Meier analyses showed that CXCL1 overexpression was correlated with worse overall survival in patients with lung cancer." (PMID 33223508, 2020). "Meanwhile, the lung cancer cell lines (A549, H1975, H1299, H1650 and PC-9) showed a remarkably higher expression level of CXCL1 compared with HBE cell line, showing an opposite expression pattern of SETD2." (PMID 33223508, 2020). "To further investigate the negative regulation of SETD2 on CXCL1 in lung cancer, we examined the correlated expression between SETD2 and CXCL1." (PMID 33223508, 2020). "Results indicated that the CXCL1 expression was down-regulated by SETD2 overexpression in lung cancer cells H1650 and PC-9, while SETD2 deletion up-regulated the expression of CXCL1 in these two cell lines." (PMID 33223508, 2020). "The meta-analysis demonstrated that CXCL1 mRNA level was increased in lung cancer tissues and high level of CXCL1 indicated tumor progression in lung adenocarcinoma." (PMID 31998654, 2019). "In order to verify the prognostic value of CXCL1 in lung cancer, we analyzed 20 published GEO databases mainly containing NSCLC patients and corresponding clinicopathological parameters." (PMID 31998654, 2019). "In vitro study confirmed that secretion of CXCL1 protein was significantly suppressed by DACH1 in lung cancer cell lines A549 and SKLU-1." (PMID 31998654, 2019). "Tumor-derived CXCL1 promoted the growth of lung cancer by recruiting neutrophils from peripheral blood into tumor tissues." (PMID 31998654, 2019). "Through immunohistochemical analysis, we found that CXCL1 protein expressed in ADC was higher than in other kinds of lung cancer." (PMID 31998654, 2019). "Docetaxel), which has been implicated in promoting inflammatory lymphangiogenesis and lymph node metastasis in an aggressive lung cancer model, and CXCL1 (p < 0.05, IgG v." (PMID 29976154, 2018). "Compared to naïve mice, serum levels of CXCL1 in 3LL lung cancer bearing mice were significantly increased." (PMID 27446967, 2016). "In conclusion, tumor-derived CXCL1 contributes to neutrophils infiltration in lung cancer which promotes tumor growth." (PMID 27446967, 2016). "Then, to investigate the roles of CXCL1 in lung cancer growth in vivo, 3LL transfected cells (NC or shCXCL1) were subcutaneously inoculated into C57BL/6J mice." (PMID 27446967, 2016). "In this study, we found that the level of CXCL1 in serum was significantly upregulated in 3LL lung cancer bearing mice." (PMID 27446967, 2016). "In conclusion, 3LL tumor-derived CXCL1 contributes to TANs infiltration in lung cancer which promotes tumor growth." (PMID 27446967, 2016). "IL-8/CXCL1 is a pro-angiogenic factor as well as a chemotactic factor for neutrophil recruitment to the lungs during emphysema and lung cancer." (PMID 25505466, 2014). "CXCL1 expression was negatively correlated with lung cancer survival in patients." (PMID 38918360, 2024). "Moreover, it has been discovered that transforming growth factor-β1 (TGFβ1) can promote the stem-like characteristics of lung cancer by inducing the expression of CXCL1." (PMID 38918360, 2024).
lung cancer (continued). "CXCL1 may also be important in the function of lung cancer stem cells, cells that divide infrequently and have high expression of DNA repair enzymes and transporters that excrete xenobiotics, particularly anticancer drugs, outside the cell." (PMID 38673949, 2024). "Furthermore, studies have shown that tumor necrosis factor (TNF) and vascular endothelial growth factor (VEGF) can stimulate the expression of CXCL1 in human lung carcinoma epithelial cells 29-31." (PMID 39132161, 2024). "Next, we assessed whether TRIM28 alters CXCL1 expression in murine and human lung cancer cell lines." (PMID 37865804, 2023). "However, another study has reported that miR141-CXCL1-CXCR2 signaling–induced Treg recruitment regulates the metastasis and survival of non–small cell lung cancer; therefore, the type of immune cells that CXCL1 recruits in the TIME should be further explored." (PMID 35754838, 2022). "DT treatment resulted in decreased expression of CCL2 and C-X-C motif chemokine ligand 1 (CXCL1) and increased expression of IL-8, blocking the ability of macrophages to promote lung cancer cell migration and the recruitment of macrophages by lung cancer cells." (PMID 36212483, 2022). "Moreover, CXCL1 (also known as Gro-1) expressed by mouse and human lung cancer cell lines, fosters TAN recruitment to the tumor." (PMID 34168563, 2021). "TQ also suppressed the production of CXCL1 in the lung cancer lines NCI-H460 and NCI-H146." (PMID 33920708, 2021). "We detected the expression of CXCL1 in normal and lung cancer tissues by IHC staining." (PMID 31998654, 2019). "Previous finding demonstrated that tumor derived CXCL1 promoted the growth of lung cancer, our study suggested that the tumor suppress function of DACH1 might be through inhibiting CXCL1." (PMID 31998654, 2019). "Among these kinds of lung cancers, the CXCL1 expression in adenocarcinoma was the highest." (PMID 31998654, 2019). "Stable overexpressing DACH1 in cultured lung cancer cells remarkably decreased CXCL1 protein." (PMID 31998654, 2019). "Previous studies have reported CXCL1 as an important cytokine in lung cancer development." (PMID 29207614, 2017). "However, some studies investigating CXCL1 expression in non‐small cell lung cancer have demonstrated opposite results." (PMID 27682863, 2016). "Considering the significance of CXCL1 in human airway epithelium and in pathological processes such as chronic inflammation and lung cancer, in this study we screened several proinflammatory mediators and growth factors in inducing CXCL1 release in human A549 lung carcinoma epithelial cells." (PMID 23665907, 2013). "Our findings identify an important link to lung cancer development and highlight KCNA7, FOXI1, and FOXB1 as marker genes for CXCL1 cancer subgroups relevant to clinical prognosis." (PMID 40568194, 2025). "Differential expression analysis of epithelial cells showed a significant increase in expression of CXCL1, CXCL2, and HDGF in KRASG12D-driven lung cancer samples compared with non–KRAS-driven lung cancer." (PMID 39782689, 2025). "Also, high CXCL1 expression in lung cancer cells may result from epigenetic changes." (PMID 38673949, 2024). "For example, increased CXCL1 and PIGF expression promotes the expansion of lung CSCs, which in turn leads to the recurrence of lung cancer." (PMID 36411463, 2022). "A study observed that the levels of CXCL1, CXCL2, CXCL5, CXCL7, and CXCL8 were higher in lung cancer compared to multiple other cancer types (breast, colorectal, esophageal, head and neck, and liver cancer)." (PMID 36612163, 2022). "TNF and VEGF are the major driving factors of CXCL-1 expression acting through PI-3K/AKT, JNK, and p38 MAPK signalling mechanisms in human lung carcinoma's epithelial cells." (PMID 34336101, 2021). "For example, tumor necrosis factor (TNF) and vascular endothelial growth factor (VEGF) stimulated CXCL1 expression via JNK, p38 MAPK, and PI-3K/Akt signaling pathways in human lung carcinoma epithelial cells." (PMID 31998654, 2019).
lung cancer (continued). "CXCL1 functions through CXCR2, a G protein-coupled receptor that transactivates EGFR in ovarian and lung cancers." (PMID 26462152, 2015). "For lung cancer, high intra-tumoral concentrations of CXCR2 ligands (CXCL1, CXCL5, and CXCL8) and type 2 cytokines IL-4, IL-5, IL-10, and IL-13 have been reported for non-small cell lung cancer." (PMID 26231039, 2015). "Using the histone deacetylase inhibitor (HDACi), Trichostatin A (TSA), an induction of CXCL8 and CXCR1/2 in both the normal (HBEC4) and lung cancer cell lines (A549 and SKMES-1), with a concomitant decrease in CXCL1–3 (SKMES-1, p<0.05) was observed." (PMID 21298036, 2011). "Based on the cytokine array of supernatants derived from coculture, CCL2 and CXCL1 were elevated in three lung cancer cell lines (HCC4006, A549, and H1975) irrespective of coculture." (PMID 36612121, 2022). "In addition, the EVs isolated from the serum of lung cancer patients also stimulated NK cells to produce VEGF, CXCL1 and S100A8, which contributed to angiogenesis and immune suppression in the TME." (PMID 34944871, 2021). "We also found that NK cells from lung cancer patients had lower expression of CD226 on their surface and exhibited a pro-inflammatory, pro-angiogenic and tumorigenesis phenotype by expressing VEGF, CXCL1, CXCL8, S100A8 and MMPs." (PMID 34944871, 2021). "Therefore, we performed the correlation analysis between CXCL1 and DACH1 in lung cancer cell lines and cancer tissues." (PMID 31998654, 2019). "In breast and lung cancer models, TNF-α has been shown to modulate a chronic inflammatory circuit (TNF-α → CXCL1/2 → MDSC recruitment → S100A8) that disrupts the TME and facilitates chemoresistance and metastasis; interruption at any point in this cascade may markedly reduce tumors’ aggressiveness." (PMID 40430573, 2025). "Our results showed that hypoxic lung cancer-derived EVs increased the polarization of NK cells to dNK-like cells with pro-angiogenic phenotypes, which have the ability to support angiogenesis in vitro with several soluble factors including, VEGF, CXCL1/2 and IL-8." (PMID 34944871, 2021). "In contrast, both pre- and clinical data have shown that K-ras mutant lung cancers demonstrate significant infiltration of multiple inflammatory cells, such as myeloid cells, CD8+ T cells, regulatory T cells (Tregs), IL-17-producing lymphocytes, and inflammatory cytokines (e.g., IL-6, IL-8, CXCL1)." (PMID 32039025, 2019). "However, the mouse epithelial cell line MLE did not secrete CXCL1, suggesting lung cancer cells could express and secrete higher levels of CXCL1." (PMID 27446967, 2016). "Data from Gene Expression Profiling Interactive Analysis (GEPIA) 25 analysis confirmed a significantly positive correlation of MARCKS expression with TNFR, RELA, BCL2A1, CXCL1, RELB or TNF-alpha in lung cancer samples but not in normal lung tissues." (PMID 33754052, 2021).
pancreatic cancer (57 papers, 2013 to 2025). "Upon overexpression of Col5a1 in Ccn1‐deficient pancreatic cancer cells, the expression of Cxcl1 and Cxcl5 were upregulated." (PMID 40287974, 2025). "At the transcript level, mRNA expression of Ccl2, Ccl7, Cxcl1, Cxcl3, and Csf2 was markedly downregulated in Ccn1‐deficient pancreatic tumors, whereas Cxcl5, Csf1, and Csf3 expression remained unchanged, and Ccl20 mRNA was elevated." (PMID 40287974, 2025). "Then, activation of CXCR2 by CXCL1 causes the proliferation of the transformed cell and thus further development of pancreatic cancer." (PMID 37408240, 2023). "Mutation in the KRAS gene, common in pancreatic cancer, leads to an increase in CXCL1 expression as well as other CXCR2 ligands." (PMID 37408240, 2023). "Other factors cause an increase in CXCL1 expression in pancreatic tumor cells." (PMID 37408240, 2023). "Increased CXCL1 expression in pancreatic cancer tumors may also be caused by a disruption in the function of metaplastic tuft cells, which are solitary chemosensory cells." (PMID 37408240, 2023). "The expression of CXCL1, 3, 5, and 8 were associated with the stages of pancreatic cancer." (PMID 34439306, 2021). "Additionally, through the Fap2 adhesin, Fn interacts with pancreatic cancer cells, promoting Fn infection in pancreatic cancer by causing infected tumor cells to release cytokines such as GM-CSF, CXCL1, IL-8, and MIP-3α, thereby promoting further tumor progression." (PMID 39860963, 2024). "In pancreatic cancer, Macro_APOE activated CXCL1 and CXCL5 expression through LDL receptor and NF-κB signaling in tumor cells, thereby establishing immunosuppressive niches." (PMID 40963562, 2025). "In pancreatic cancer, iCAFs also show high Lamin A/C and pro-inflammatory cytokines such as IL-6, IL-8, CXCL1, and CXCL12." (PMID 40846900, 2025). "CXCL1, a chemokine closely related to inflammation and immune responses, plays a key role in promoting pancreatic cancer cell metastasis and conferring chemoresistance." (PMID 40959217, 2025). "They demonstrated that the F. nucleatum group promoted the C-X-C motif chemokine ligand 1 (CXCL1) secretion from pancreatic cancer cells, leading to cancer progression through autocrine signaling." (PMID 41471188, 2025). "Conversely, APOE assumes an immunosuppressive role in the pancreatic cancer microenvironment by upregulating the expression of CXCL1 and CXCL540." (PMID 39990672, 2025). "GM-CSF substantially speeds up the proliferation of pancreatic cancer cells, and CXCL1 is essential for metastasis and chemotherapy resistance in pancreatic cancer." (PMID 39860963, 2024). "This research has demonstrated that intratumoral Fn stimulates tumor growth by increasing pancreatic cancer cells’ autocrine production of CXCL1." (PMID 39860963, 2024). "In pancreatic tumors, CXCL1 in concert with CSF3 facilitate G-MDSC infiltration and establishment of an immunosuppressive microenvironment that limits T cell frequency and function." (PMID 37988164, 2024). "Necroptotic pancreatic cancer cells induce peri-necroptotic immune suppression and invasion through CXCL1, CXCL5 and SAP130-Mincle signalling." (PMID 38926796, 2024). "Another study showed that the necrosome can promote pancreatic cancer through C-X-C motif chemokine ligand 1 (CXCL1) and Mincle-induced immunosuppression." (PMID 37061535, 2023). "Pancreatic stellate cells secrete exosomes that increase CXCL1 expression in pancreatic cancer cells." (PMID 37408240, 2023). "Among a variety of chemokines/cytokines known to recruit and/or generate MDSCs in tumor sites, we found significant elevations in Cxcl1, Cxcl2, Csf2, and Tgfb1 in the pancreatic tumor tissues of PKR mice." (PMID 37814340, 2023). "In contrast to the effect of TRIM37 knockdown in pancreatic cancer on CXCL-1 and G-CSF, there was an increase in the production of IL-12, MCP-1, and MIP-1α." (PMID 35163097, 2022).
pancreatic cancer (continued). "CAFs alter the pancreatic cancer microenvironment by the secretion of growth factors such as C-X-C motif chemokine ligand 1 (CXCL1), CXCL12, C-C motif chemokine ligand 8 (CCL8), stromal cell-derived factor-1 (SDF-1), IL-6, IL-11, VEGF and others." (PMID 35883598, 2022). "The upregulation of Cxcl1,2 by cancer cells in response to gemcitabine treatment was further confirmed in flow cytometry sorted disseminated pancreatic cancer cells." (PMID 35022267, 2022). "RIPK3/RIPK1 regulation of CXCL1 in pancreatic cancer restricts infiltration of highly immunogenic T or B cells to promote tumor migration and invasion." (PMID 35965497, 2022). "The results on pancreatic cancer data showed that 12 genes were up-regulated (CXCL1, 2, 3, 5, 6, 8, 9, 10, 13, 14, 16, and 17)." (PMID 34439306, 2021). "We were able to show that the serum of exercise-trained patients with advanced-stage pancreatic cancer (PC) leads to the release of certain myokines, such as C-X-C motif ligand 1 (CXCL1), Interleukin 10 (IL10), and C-C motif chemokine ligand 4 (CCL4), from contracting skeletal muscle." (PMID 39518934, 2024). "CXCL1 is also involved in chemotherapy resistance in pancreatic cancer patients." (PMID 37408240, 2023). "CXCL1, together with other CXCR2 ligands, causes angiogenesis, and it may also be important in the metastasis of pancreatic cancer." (PMID 37408240, 2023). "Mechanistically, we revealed that SETD2‐H3K36me3 loss directly downregulated Cxadr expression in pancreatic tumor cells, allowing for PI3K‐AKT activation and the release of excessive CXCL1 and GM‐CSF, which attracted neutrophils and reprogrammed them toward an immunosuppressive phenotype." (PMID 36453584, 2023). "The low importance of CXCL1 in the development of pancreatic cancer tumors has been shown in animal experiments and it has been suggested that this chemokine is more important in pancreatic cancer metastasis." (PMID 37408240, 2023). "CXCL1 is significant in the early stages of pancreatic cancer transformation." (PMID 37408240, 2023). "In pancreatic cancer tumors, particularly in pancreatic ductal adenocarcinoma, there may be an upregulation of CXCL1 expression relative to healthy tissue." (PMID 37408240, 2023). "CXCL1 is highly expressed in human pancreatic cancer patient specimens." (PMID 35159011, 2022). "Moreover, CXCL1 directly represses T cell infiltration and mitigates sensitivity to immunotherapy in pancreatic cancer." (PMID 31991604, 2020). "Consistent with previous reports, we demonstrated that knockdown of Cxadr could facilitate AKT activation and E‐cadherin downregulation in pancreatic tumor cells.[8a] In addition, the mRNA levels of both Cxcl1 and Csf2 were also upregulated in step with AKT phosphorylation." (PMID 36453584, 2023). "We found higher levels of Cxcl1, Cxcl2, and TGFβ mRNAs bound to mutant Regnase-1 protein than those bound to wild-type Regnase-1 protein, suggesting that Regnase-1 may directly bind to and degrade these cytokines/chemokines in pancreatic tumor cells." (PMID 37814340, 2023). "For example, the neutrophil-enriched pancreatic cancer clones increase CXCL1 expression that is mediated at the epigenetic level via a combination of more accessibility of the promoter region, enrichment of the active H3K4me3 histone marker and activity of c-Myc that governs CXCL1 expression." (PMID 37928272, 2023). "In pancreatic cancer, APOE+ macrophages inhibit CD8 T cell infiltration by producing CXCL1 and CXCL528." (PMID 40835684, 2025). "In our previous study, we observed that a combination of CXCL1, IL10, and CCL4 significantly impacted pancreatic cancer cells." (PMID 39518934, 2024). "Another source of CXCL1 in pancreatic tumors is inflammatory CAF; in pancreatic cancer, these are stromal fibroblasts." (PMID 37408240, 2023).